JAK2 (Janus kinase 2)
Diseases named in the same sentence as JAK2 in open-access papers (continued):
Sharing a sentence is not in itself a finding about the gene and the disease.
atherosclerosis (continued). "FABP4 is a well‐known inflammatory regulator involved in various inflammatory diseases such as ischemic stroke, non‐alcoholic steatohepatitis, and atherosclerosis by activating the JNK, NF‐κB, and JAK2/STAT2 signaling pathways in macrophages." (PMID 38884133, 2024). "In contrast to TET2 and DNMT3A, where NLRP3 inflammasome activation appears predominant as a mechanism that drives accelerated atherosclerosis, recent data suggest that ASXL1 and JAK2 CHIP provoke activation of the AIM2 inflammasome." (PMID 39352379, 2024). "The results revealed that, compared to the ND group, the HFD group exhibited conspicuous co-localization of α-SMA+CD68+KLF4+, α-SMA+CD68+p-JAK2+, and α-SMA+CD68+p-STAT3+ at the foam cell aggregation regions of atherosclerosis plaque-rich aortic." (PMID 39062998, 2024). "As expected, we found that JAK2 and STAT3 levels of rats in the diabetic atherosclerosis group were negatively correlated with 25(OH)D concentrations and significantly decreased after vitamin D intervention." (PMID 35082965, 2022). "Here, it has been shown experimentally that Jak2 mutant macrophages induce DNA replication stress, activate the AIM2 inflammasome and thereby aggravated atherosclerosis." (PMID 36355225, 2022). "Various studies have shown that the activation of JAK2/STAT3 signaling pathway promotes the proliferation of VSMCs and involves in the progression of atherosclerosis by modulating apoptotic regulatory proteins such as B cell lymphoma-2 (Bcl-2) and cyclinD1." (PMID 35082965, 2022). "The JAK2/STAT3 signaling pathway is a classical inflammatory signaling pathway that regulates macrophage polarity toward the M1 phenotype and modulates the secretion of inflammatory factors (e.g., TNF-α), which exacerbates the course of atherosclerosis." (PMID 40647133, 2025). "The JAK2/STAT3 pathway promotes macrophage polarization toward the M1 phenotype, increasing the production of inflammatory molecules such as tumor necrosis factor‐alpha (TNF‐α), thereby accelerating the development of atherosclerosis." (PMID 40166646, 2025). "Our findings provide, for the first time, novel evidence that quercetin suppresses the phenotypic switch of VSMCs to macrophage-like cells by inhibiting the JAK2/STAT3 pathway and reducing KLF4 expression, thereby preventing foam cell formation and attenuating atherosclerosis." (PMID 39062998, 2024). "In addition, CD36, JAK2, STAT3, and CDC42 are essential in reducing lipid accumulation and atherosclerosis in foam cells." (PMID 36903257, 2023). "Furthermore, IL-6 and other cytokines are able to activate the JAK2/JAK2-STAT3/STAT3 pathway in fibroblasts and endothelial cells, which facilitates the process of endothelial damage, atheroma formation and atherosclerosis." (PMID 37735399, 2023). "In order to assess the effects of systemic exposure to JAK2 inhibitors on atherosclerosis, we fed ApoE-null mice with HCD with or without ruxolitinib for 16 weeks, starting at 6 weeks of age, and assessed for atherosclerotic burden." (PMID 35169231, 2022). "Furthermore, we found that JAK2 and STAT3 phosphorylation were up-regulated in rabbits with atherosclerosis when compared with those of the control group, followed by the expression of SOCS3 was also increased due to the activation of JAK2 and STAT3." (PMID 32169038, 2020). "Taking into account our results, we hypothesized that the high level of plasma lipids, increased the secretion of IL-6, IFN-γ and TNF-α, subsequently activating JAK2/STAT3 to induce and aggravate atherosclerosis." (PMID 32169038, 2020).
atherosclerosis (continued). "Mechanistically, we found that JAK2 and STAT6 were suppressed to a greater degree during monocyte-to-macrophage differentiation in patients with SLE compared with controls, especially among patients with atherosclerosis." (PMID 25011540, 2014). "Mutations in genes such as ten-eleven translocation-2 (TET2), Janus kinase 2 (JAK2), and DNA methyltransferase 3 alpha (DNMT3A), which are frequently observed in patients with CH, have been shown to promote inflammatory responses and alter macrophage function in the context of atherosclerosis." (PMID 40244103, 2025). "The potential for JAK2 inhibitors to protect against atherosclerosis has not been tested." (PMID 32086626, 2020). "Considering the important role of JAK2/STAT3/SOCS3 signaling pathway played in the inflammatory process in atherosclerosis, the potentially therapeutic strategy may be expected for the treatment of patients with atherosclerosis." (PMID 32169038, 2020). "These inhibitors inhibit the JAK2/STAT3 signaling pathway in a similar way, which indicates that they may function by suppressing immune and inflammatory responses during the development of atherosclerosis." (PMID 31588227, 2019). "Many of the genes differentially regulated during monocyte-to-macrophage differentiation (downregulated genes include JAK2, STAT6, TLR8, and TLR2, and upregulated genes include VEGFB, TGFB1, FN1, IL-1R2, SCARB1, MSR1, and CD163) have been previously reported in the pathogenesis of atherosclerosis." (PMID 25011540, 2014). "Finally, we subjected M-Jak2 KO and WT mice on HCD with TO901317 or vehicle for 3 weeks and found that plaque burden was attenuated in M-Jak2 KO mice exposed to TO901317, showing the critical role of cholesterol efflux that was regulated by JAK2 in determining atherosclerosis progression." (PMID 35169231, 2022). "However, whether ruxolitinib plays a key role in atherosclerosis process and JAK2/STAT3/SOCS3 signaling pathway is still not well understood." (PMID 32169038, 2020). "Indeed, our results demonstrate hyperphosphorylation of both AMPK and JAK2/STAT3 signalling through MSI-1436 in acute oxLDL-challenge, which may result in a more favourable inflammatory phenotype and make beneficial effects of the compound in early atherosclerosis feasible." (PMID 37828508, 2023).
Obesity (65 papers, 2007 to 2026). Accumulation of substantial excess body fat. "Our data provides evidence that ablating Jak2 or Stat3 in myeloid cells reverses the phenotype of obesity/ATM inflammation-linked insulin resistance in vivo." (PMID 40801626, 2025). "To test the role of myeloid cell intrinsic Jak2–Stat3 signaling inducing obesity-associated insulin resistance, we generated control (Mx1-Cre/Jak2+/+) mice and mice with the hematopoietic cell ablation of Jak2 (Mx1-Cre/Jak2−/−)." (PMID 40801626, 2025). "These mice exhibited similar increased weights after being fed an HFD for 12 weeks, although there was some reduction in obesity-associated mass detected in the Jak2−/− mice compared with the Jak2+/+ mice after 14 weeks of an HFD." (PMID 40801626, 2025). "Findings from a Mendelian randomization study involving 1021 participants suggest a causal association between the methylation of Janus kinase 2 (JAK2) and obesity." (PMID 39355507, 2024). "Obesity provides major attenuation of NFκB signaling via SOCS3-associated JAK2 inhibition, and then suppresses WNK4 activity." (PMID 34489970, 2021). "Of note, a number of negative regulators of JAK2, including SOCS3, PTP1B, RPTPe, and TCPTP, have been reported to promote obesity, supporting the notion that JAK2 inhibitory molecules increase risk for leptin resistance, obesity, and metabolic disease." (PMID 32251290, 2020). "FNDC5 attenuates obesity-induced cardiac hypertrophy by inactivating JAK2/STAT3 associated-cardiac inflammation and oxidative stress." (PMID 30940158, 2019). "Our study addresses the essential role of macrophage JAK2 in the pathogenesis to obesity-associated inflammation and insulin resistance." (PMID 28794431, 2017). "Jak2 or Stat3 may therefore represent potential therapeutic targets for improving obesity-linked insulin resistance." (PMID 40801626, 2025). "The study demonstrated the ability of the JAK inhibitor to correct abnormalities in insulin signaling in the liver and skeletal muscle, shedding further light on the pilot role of JAK2 in the regulation of different metabolic processes implicated in the development of diabetes and obesity." (PMID 37701031, 2023). "To investigate the relationship between CHIP and obesity, we analyzed several mouse models harboring common CHIP mutations: Tet2, Dnmt3a, Asxl1, or Jak2 on the background of LepOb/Ob (Ob/Ob) mice to mimic the human pre-LHSCs/PCs condition occurring in individuals with obesity." (PMID 37071471, 2023). "Thus, EGCG can alleviate the obesity-associated neuroinflammation of the hypothalamus via regulating JAK2/STAT3 signaling pathway." (PMID 31614951, 2019). "Importantly, PTP1B-deficient mice display the resistance to diet-induced obesity, augmented energy expenditure, hypersensitivity to leptin, and enhanced phosphorylation levels of JAK2 and STAT3 in the hypothalamus." (PMID 30383868, 2018). "The reduced VAT inflammation could also contribute to the reduced adipocyte hypertrophy and enhanced adipogenesis during diet-induced obesity in our macrophage Jak2-deficient mice." (PMID 28794431, 2017). "On the other hand, JAK2 deficiency in adipocytes promotes obesity and insulin resistance." (PMID 28794431, 2017). "However, the function of macrophage JAK2 in the inflammatory response and insulin resistance caused by diet-induced obesity remains unknown." (PMID 28794431, 2017). "Inhibition of LepRb intracellular signaling by JAK2 dephosphorylation is a potential contributor to leptin resistance in obesity." (PMID 41251447, 2025). "In this study, we investigated the role of Jak2 and Stat3 in myeloid cells/macrophages in modulating obesity-induced inflammation and insulin resistance." (PMID 40801626, 2025). "As FFAs can bind to inflammatory receptors such as TLR4 that drive cytokine production, it is possible that Jak2/Stat3 mediates FA binding to TLR4 to potentiate adipose tissue inflammation during obesity." (PMID 40801626, 2025).
Obesity (continued). "Collectively, these data indicate that obesity/FFAs contribute to M1 cytokine expression in macrophages through activating Jak2/Stat3 signaling." (PMID 40801626, 2025). "PTP1B directly dephosphorylates JAK2, and PTP1B-deficient mice display reduced food intake, increased leptin sensitivity, and resistance to diet-induced obesity." (PMID 41516046, 2025). "Reticuline alleviates airway inflammation in obesity‐related asthma by inactivating the JAK2/STAT3/SOCS3 and p38 MAPK/NF‐κB signaling pathways." (PMID 38286741, 2024). "PTP1B can serve to dephosphorylate and inactivate the IR and the leptin receptor–associated kinase JAK2; this is what laid the foundation for excitement about PTP1B as a therapeutic target for diabetes and obesity." (PMID 35866483, 2022). "Fibronectin type III domain-containing protein 5 attenuates cardiac hypertrophy induced by obesity by inactivating JAK2/STAT3-related cardiac inflammation and oxidative stress." (PMID 35812340, 2022). "Protein tyrosine phosphatase 1B (PTP1B) negatively regulates leptin signaling by dephosphorylating JAK2, and the increased activity of PTP1B is implicated in the pathogenesis of obesity." (PMID 30383868, 2018). "Studies revealed that obesity-induced thyroid tumor growth and cancer progression are mediated by the activated phosphorylation of oncogenic JAK2 and STAT3 transcription factors." (PMID 28750624, 2017). "SH2B1 enhances leptin signaling through the augmentation of JAK2 activity, and deletions or mutations in the SH2B1 gene are known to be associated with severe obesity in humans and mice." (PMID 28912580, 2017). "Obesity-induced thyroid tumor growth and cancer progression have been shown to be mediated by the enhancement of phosphorylation of oncogenic JAK2 and STAT3 transcription factors." (PMID 27050378, 2016). "In terms of a potential causal role of leptin as a driver of breast carcinogenesis, preclinical data show that leptin regulates JAK2/STAT3 and inflammatory cytokine related signaling, which is altered by obesity and reregulated via weight loss." (PMID 26132992, 2015). "Our findings of a reduction in ObRb and/or Jak2 and pSTAT3 protein expression levels are similar to previous reports for effects of diet-induced obesity and consumption of high-fat diets on these proteins in the hypothalamus." (PMID 18162139, 2007). "Our demonstration that Jak2/Stat3 is persistently activated in the fat-laden adipose tissue microenvironment has important implications for understanding how pro-inflammatory ATM phenotypes are amplified during obesity." (PMID 40801626, 2025). "Using mice with a Jak2 deficiency in the myeloid compartment and Stat3 ablation in myeloid cells, we identify cell-intrinsic Jak2/Stat3 signaling as a critical driver of the pro-inflammatory ATM phenotype in obesity." (PMID 40801626, 2025). "Moreover, increased serum leptin in obesity suppressed anti-Mullerian hormone gene expression through the JAK2/STAT3 pathway." (PMID 36726106, 2023). "PTP-1B, a non-transmembrane PTP, down-regulate leptin/STAT3 signaling via indirectly inactivating JAK2, which may be a new target for the treatment of obesity induced by leptin resistance." (PMID 33849593, 2021). "Jak2 activation has been shown to be the primary pathway by which the LepR functions on the neuroendocrine system and STAT3 signaling has been implicated in promoting obesity-mediated cancer progression." (PMID 33019728, 2020). "In contrast, JAK2 deficiency in the liver, macrophages, or adipocytes protects against high-fat diet induced metabolic inflammation, suggesting that JAK2 may be a promising target for the treatment of obesity, metabolic syndrome and T2DM." (PMID 32413585, 2020). "Given that JAK2 plays a critical role in brown adipose tissue function and diet-induced thermogenesis in HFD mice, JAK2 signaling between leptin and IFNγ may play a critical role in obesity-related inflammation and metabolic disorders." (PMID 33379198, 2020).
Obesity (continued). "JAK2 might be imbalanced in patients with obesity could lead to an exaggerated immune response." (PMID 41359762, 2025). "Obesity-related chronic inflammation might promote tumor by releasing pro-inflammatory factors, such as IL-6 with anti-apoptotic and cell proliferation effect via JAK2 and PI3K/AKT, as well as TNF-α with anti-apoptotic effect via NF-kB." (PMID 40933888, 2025). "In these regions, leptin signaling is mediated by the JAK2/Stat3 pathway, in which several negative regulators of JAK2, including SOCS3 and PTP1B, have been reported to promote obesity, supporting the notion that JAK2 inhibitory molecules increase risk for leptin resistance and obesity." (PMID 32630697, 2020). "Therefore, it is worthy to examine whether JAK2/STAT3 pathway is involved in molecular mechanisms of obesity-induced cardiac hypertrophy." (PMID 30940158, 2019). "Finally, given the increased interest in the use of GH as a therapeutic agent to “treat” obesity and the intense activity in the clinical development of JAK2 inhibitors for the treatment of cancer and inflammatory diseases, this work has significant translational implications." (PMID 23782652, 2013). "Taken together, our data suggest that leptin doses mimicking hyperleptinemia in individuals with obesity were able to activate NCOA1, contributing to the activation and phosphorylation of the JAK2/STAT3 pathway." (PMID 41562922, 2026). "Matcha green tea inhibits the JAK2/STAT3 pathway, preventing hypothalamic inflammation induced by obesity." (PMID 39606571, 2024). "Taken together, we have for the first time demonstrated that SPX alleviated diet-induced obesity and ameliorated glucose and lipid metabolism by inducing the browning of white adipose, and the pro-browning action of SPX is mediated by JAK2/STAT3 pathway." (PMID 38658956, 2024). "Mechanistically, reticuline inactivated the JAK2/STAT3/SOCS3 and p38 MAPK/NF‐κB signaling pathways in obesity‐related asthma." (PMID 38286741, 2024). "Matcha green tea is crucial in preventing obesity-induced hypothalamic inflammation by blocking the JAK2/STAT3 signaling pathway, thereby aiding in the management of obesity-related metabolic syndrome." (PMID 39606571, 2024). "Previous studies reported that ponatinib can reduce inflammation of obesity and influenza due to its inhibitory effect on the two isoforms of JAK (JAK1 and JAK2)." (PMID 37333458, 2023). "Mouse models of obesity and CHIP driven by heterozygosity of Tet2, Dnmt3a, Asxl1, and Jak2 resulted in exacerbated expansion of mutant HSC/Ps due in part to excessive inflammation." (PMID 37071471, 2023). "Topological analysis and modular analysis revealed the role of HJJPD in the treatment of simple obesity by acting on SOCS-3, JAK2, LepRB, LEP, IL-6, and STAT3 and influencing the JAK2-STAT3 pathway." (PMID 35529938, 2022). "In accordance with the results of HFD-induced obesity in vivo, KBH-1 significantly up-regulated the activation of leptin-mediated signals, including AMPK and JAK2, in a time-dependent manner." (PMID 27618865, 2016). "Additionally, we further demonstrated the inhibitory effects of reticuline on the JAK2/STAT3/SOCS3 and p38 MAPK/NF‐κB signaling pathways in the HFD and OVA‐induced obesity‐related asthma models." (PMID 38286741, 2024). "In another study of obesity-related KOA, Jiang found that RES attenuated obesity-related KOA by attenuating the janus kinase 2 (JAK2)/STAT3 signaling pathway independent of the suppressor of cytokine signaling 3 (SOCS3) pair." (PMID 35959426, 2022). "Moreover, the increased SOCS3 in the hypothalamus in turn suppresses JAK2/STAT3 signaling pathway, which forms leptin resistance, leading to hyperleptinemia and obesity." (PMID 36270984, 2022). "The expression levels of LEPRB, SOCS-3, JAK2, and STAT3, and the key targets in the JAK2-STAT3 signaling pathway in liver and adipose tissue of mice in each group, were analyzed to verify the mechanism of HJJPD in the treatment of simple obesity." (PMID 35529938, 2022).
Obesity (continued). "Further studies confirmed their findings and identified that resveratrol alleviating obesity-related osteoarthritis via alleviating JAK2/STAT3 signaling pathway, which independent of SOCS3." (PMID 34215299, 2021). "Therefore, the activation of JAK2 or STAT3 in hepatocytes also ameliorates steatosis and improves lipid metabolism, which further contributes to anti-obesity action." (PMID 29874843, 2018). "Previous studies reported that negative feedback regulators of JAK2/STAT3 signal transduction increase with obesity." (PMID 27375555, 2016). "We found increased activation of MAPK/ERK, JAK2/STAT3, and PI3k/AKT signaling pathways in human leiomyoma cells as a result of adipocyte coculture, outlining the pathophysiological link between adipocyte hypertrophy in obesity and the development of uterine leiomyoma." (PMID 36771423, 2023). "This may be at least one molecular mechanism involved in the reduced B cell function in individuals with obesity, as it induces the secretion of pro-inflammatory cytokines (IL-6/TNF-α) in human peripheral blood B cells through activation of JAK2/STAT3 and p38MAPK/ERK1/2 signaling pathways." (PMID 33760825, 2021). "However, it is unclear whether FNDC5 is involved in cardiac fatty acid oxidation during obesity, and the crosstalk between PPAR-α and JAK2/STAT3 signaling or other signal transduction molecules needs further investigation." (PMID 30940158, 2019). "It was previously not known whether macrophage JAK2 contributes to the development of obesity and insulin resistance." (PMID 28794431, 2017). "These isoforms activate JAK2, but not STAT3 signaling, and, as such, are not involved in the anti-obesity effects of leptin." (PMID 27375555, 2016).